ATG7 (autophagy related 7)
Diseases named in the same sentence as ATG7 in open-access papers (continued):
Sharing a sentence is not in itself a finding about the gene and the disease.
vitiligo (6 papers, 2016 to 2025). Generalized well circumscribed patches of leukoderma that are generally distributed over symmetric body locations and is due to autoimmune destruction of melanocytes. "Consistently, autophagy-related 7 (Atg7)-deficient mice present reduced melanin production, intense oxidative stress, and senescent melanocytes, resembling vitiligo melanocytes." (PMID 41007740, 2025). "To investigate the possible involvement of autophagy in vitiligo, we initially determined the relative mRNA abundance of some Atg transcripts (Atg5, Atg7, Atg8) by quantitative reverse-transcriptase PCR." (PMID 33767135, 2021). "The expression levels of Atg7 and Atg8 were significantly higher in non-lesional vitiligo melanocytes (VHMs) than in control cells (NHMs), while the level of Atg5 showed a tendency to increase, although this was not statistically significant." (PMID 33767135, 2021). "We demonstrated that, although Atg5 and Atg8 mRNAs were not upmodulated, vitiligo fibroblasts showed a tendency to exhibit elevated autophagy, as assessed by increases of Atg7 gene expression, LC3, and Beclin I production concurrently with the down-modulation of SQSTM1/p62." (PMID 33767135, 2021). "Increased ATG7 and ATG8 expression were also found in melanocytes in vitiligo non-lesions." (PMID 35406685, 2022).
Autoimmunity (5 papers, 2012 to 2018). The occurrence of an immune reaction against the organism's own cells or tissues. "Interestingly, the phenotypes of autoimmunity reported in Atg7 deficient mice, align with lymphoid proliferation and increased cellularity we observe in Foxp3-Cre::Notch1lox/loxmice." (PMID 27267497, 2016). "Several research groups have implicated the role of ATG5, ATG7, and ATG16L1 in keratinocytes, melanocytes, and immune cells in autoimmunity and cancer." (PMID 29988591, 2018). "In contrast to previously reported mice, that had received an autophagy-deficient thymus transplant, ATG7 f/f K14-Cre mice did not suffer from autoimmunity-induced weight loss." (PMID 22719991, 2012).
cardiomyopathy (5 papers, 2015 to 2023). A disease of the heart muscle or myocardium proper. "Gain- and loss-of-function of Atg7 studies in the αB-crystallin R120G mutation (CryABR120G) model of rat desmin-related cardiomyopathy reveal the significant ability of ATG7 in reversing autophagic deficiency and maintaining physiological levels of basal autophagy." (PMID 26404030, 2015). "Identifying these specific characteristics of both molecules highlights the potential for the design of improved and less toxic ATG7 and Doxorubicin analogs with reduced cardiomyopathy." (PMID 37305823, 2023). "Conversely, in vivo overexpression ATG7 in mice improves autophagic capacity that ameliorates desmin-related cardiomyopathy." (PMID 36939901, 2023). "In mice, ATG7−/− or ATG5−/− leads to cardiomyopathy characterized by inhibited autophagy and induced mesenchymal transition and apoptosis." (PMID 36939901, 2023). "In support of this, age‐related cardiomyopathy is recapitulated in adult mice by cardiac‐specific Atg5 deletion and mTORC1 activation, whereas desmin‐related cardiomyopathy, characterized by the accumulation of cytotoxic misfolded proteins, is prevented by cardiac‐selective Atg7 overexpression." (PMID 34554626, 2021).
epilepsy (5 papers, 2017 to 2024). A brain disorder characterized by episodes of abnormally increased neuronal discharge resulting in transient episodes of sensory or motor neurological dysfunction, or psychic dysfunction. "For example, the inactivation or deletion of Atg7 which is an activator of autophagy triggers recurrent seizures and the development of epilepsy in mice." (PMID 37880579, 2023). "Knockout of ATG-7, a key molecule in the autophagy cascade, leads to spontaneous seizures in mice, implying that inhibition of autophagy is sufficient to induce epilepsy." (PMID 33132826, 2020). "Induction of autophagy and autophagy-related proteins like Atg7, LC3, and Beclin-1 by endothelial progenitor cells could be a novel therapeutic strategy in the management of epilepsy." (PMID 38006577, 2024). "The induction of autophagy and autophagy-related proteins like Atg7, LC3, and Beclin-1 by endothelial progenitor cells could be a novel therapeutic strategy in the management of epilepsy." (PMID 37880579, 2023). "Induction of autophagy and autophagy-related proteins like Atg7, LC3, and Beclin-1 might be an innovative therapeutic strategy in managing epilepsy." (PMID 37880579, 2023). "However, previous studies revealed that deletion of both Atg5 and Atg7 resulted in neurodegeneration without evidence of epilepsy." (PMID 37880579, 2023).
fibrosis (5 papers, 2016 to 2024). the formation of excess fibrous connective tissue in an organ or tissue in a reparative or reactive process. "Impaired conventional ATG7-dependent macro-autophagy in lung endothelium increased susceptibility to BLM-induced fibrosis in mice." (PMID 33746598, 2021). "Next, we detected the histology morphology of hearts from examined mice by H&E staining, and found that the myofibres were disorganized and severe cardiac fibrosis appeared in ischaemia-reperfusion-treated Atg7-deficient mice." (PMID 27512143, 2016). "Therefore, we also examined the effects of an EC-specific deletion of Atg7 on fibrosis in aging kidneys." (PMID 39199133, 2024). "In contrast, when TGFβ signaling was selectively inhibited in experimental fibrosis using the TβRI inhibitor SD-208, the induction of autophagy in bleomycin-induced fibrosis was abrogated and the levels of BECLIN1, ATG7 and p62 were comparable to those of non-fibrotic controls." (PMID 34285225, 2021).
Glucose intolerance (5 papers, 2009 to 2022). Glucose intolerance (GI) can be defined as dysglycemia that comprises both prediabetes and diabetes. "POMC-specific loss of LEPR or ATG7 increased body weight in both sexes, but only male pomc-LepR KO mice and female pomc-ATG7 KO mice developed glucose intolerance." (PMID 36120438, 2022). "Our data suggests that antioxidant treatment with NACis particularly beneficial in preventing the glucose intolerance phenotypeobserved following deletion of Atg7 within β cells." (PMID 20157526, 2009).
ischemic stroke (5 papers, 2017 to 2024). A stroke disorder caused by obstruction of blood flow to the brain, due to thrombotic (local blood clot formation) or embolic (due to a blood clot or other material traveling from another site) event. "ATG7, which has been implicated in autophagy, could provide novel insights into the genetic basis of ischemic stroke." (PMID 29123153, 2017). "In the present study, we identified the early protective role of endothelial Atg7 deletion on the brain damage at the acute phase of ischemic stroke." (PMID 30555402, 2018). "The role of Atg7 in ischemic stroke and reperfusion injury has been controversial in previous studies." (PMID 30555402, 2018). "Additionally, Foxo3 induced autophagy in ischemic stroke damage by directly promoting the expression of ATG7 as a transcription factor." (PMID 39021183, 2024). "Based on this work, the pharmacological modulation of Atg7 could be a future direction for the clinical treatment of ischemic stroke." (PMID 30555402, 2018). "Thus, it will be interesting to clarify the role of Atg7 in the recovery phase of ischemic stroke in future study." (PMID 30555402, 2018). "The protein expression levels of pAMPK, mTOR, Beclin 1, and autophagy-related protein 7 (ATG7) were reduced in the brain tissue of the simvastatin pretreated and treated groups compared to the ischemic stroke group." (PMID 39707228, 2024).
Lewy Body disease (5 papers, 2020 to 2025). "Decreased levels of Atg7 (autophagy related 7) and increased levels of mTOR have been demonstrated in patients with Lewy body disease and in a model of α-synucleinopathy, suggesting possible impairment of autophagy." (PMID 35408992, 2022). "Impaired autophagy in neurons through genetic disruption of MAP1LC3A/B along with ATG5/ATG7 induced neuropathologic features in dementia with Lewy bodies (DLB) patients." (PMID 33419148, 2021). "In addition, increased mTOR and decreased ATG7 were observed in the brains of dementia with Lewy bodies (DLB) patients and α-synuclein transgenic mice, with colocalization of α-synuclein and LC3." (PMID 39949604, 2025).
myocardial ischemia (5 papers, 2019 to 2024). A disorder of cardiac function caused by insufficient blood flow to the muscle tissue of the heart. "MiR-143 expression relieves myocardial ischemia/reperfusion (I/R) injury by downregulating Atg7 expression." (PMID 38553562, 2024). "We here show that Trx1 promotes autophagy during myocardial ischemia through transnitrosylation of Atg7." (PMID 36480290, 2023). "Although myocardial ischemia primarily promotes both oxidation and S-nitrosylation of Trx1, concurrent reduction of Trx1 by Atg7 induces transnitrosylation of Atg7 at Cys402 and stimulation of the E1-like activity of Atg7." (PMID 36480290, 2023). "We here show that the thiol-disulfide exchange and the NO transfer are coupled, allowing oxidized Trx1 to mediate a salutary effect in the heart through transnitrosylation of Atg7 during myocardial ischemia." (PMID 36480290, 2023). "Here we show that Trx1 acts as an endogenous transnitrosylase for cardiac proteins, including Atg7, under basal conditions and during myocardial ischemia, and that Cys73 plays an essential role in transferring NO to its targets." (PMID 36480290, 2023). "In addition, lncRNA CHRF enhances autophagy and exacerbates myocardial ischemia/reperfusion injury by modulating the miR-182-5p/Atg7 pathway." (PMID 38553562, 2024). "However, S-nitrosylation of Atg7 was significantly increased after 30 minutes of myocardial ischemia." (PMID 36480290, 2023). "Based on these results, we further investigated how NO is transferred from Trx1 to Atg7 during myocardial ischemia and whether oxidized Trx1 mediates protection against myocardial ischemia." (PMID 36480290, 2023). "During acute myocardial ischemia, autophagy has been shown to confer cardioprotection, as deletions/mutations of proteins involved in the formation of the autolysosome (DRAM2, Ulk1, Atg7) either induce baseline cardiac dysfunction, or exacerbate MI pathophysiology." (PMID 35614179, 2022). "Thus, the oxidoreductase activity of Atg7 not only regenerates Trx1 but also stimulates transnitrosylation of Atg7 itself, thereby playing an essential role in mediating protection of the heart against myocardial ischemia." (PMID 36480290, 2023). "DRAM1 showed a significant direct interaction only with Atg7, which regulated the autophagic flow of DRAM1-Atg7-Atg12/Atg5 under the stress condition of myocardial ischemia, thereby alleviating autophagic flow and regulating the mechanism of myocardial cell protection." (PMID 38414735, 2024). "Since Trx1-C73S–KI and Atg7-C402S–KI mice are systemic KI mice, however, we cannot exclude involvement of Trx1-mediated Atg7 transnitrosylation in non-myocytes in mediating the protection against myocardial ischemia." (PMID 36480290, 2023).
renal carcinoma (5 papers, 2018 to 2025). A carcinoma arising from the epithelium of the renal parenchyma or the renal pelvis. "Western blot analysis demonstrated that CSF2 treatment increased autophagy-related proteins LC-3 II/I, ATG7, and Beclin1 in co-cultured renal cancer cells (P < 0.001)." (PMID 41216204, 2025). "Our previous study showed that autophagy–related protein 7 (ATG7) be a new biomarker for the targeted therapy of renal cancer." (PMID 34733376, 2021). "The downregulation of ATG7 and beclin-1 also prevented the combined treatment-induced apoptosis in human renal carcinoma Caki, ACHN, and A498 cells." (PMID 29849119, 2018). "We previously showed that ATG7 is a critical biomarker for renal cancer prognosis." (PMID 34733376, 2021). "ATG7 and ULK4, which are core autophagy genes, showed effective selection of mutations in renal cancer and endometrial cancer, respectively, indicating that the expression and mutation of ULK4 may be closely related to autophagy." (PMID 33937013, 2021).
Stroke (5 papers, 2018 to 2025). Sudden impairment of blood flow to a part of the brain due to occlusion or rupture of an artery to the brain. "Our findings established the novel regulatory role of Atg7 in cerebral vessels associated with the inflammatory reactions during stroke." (PMID 30555402, 2018). "At 24 h, levels of Beclin1 were decreased in stroke females compared to sham, and levels of ATG7 were elevated in the stroke females compared to sham." (PMID 34359998, 2021). "Imputation analysis also supported the association between three SNPs (rs2594966, rs2594973, rs4684776) in ATG7 gene and stroke-small-vessel occlusion (SVO)." (PMID 31510945, 2019). "Depletion of Atg7 in brain endothelium has a neuroprotective effect against the ischemia/reperfusion-induced acute cerebral injury during stroke." (PMID 30555402, 2018). "Cerebral endothelial ATG7 was reported that could modulate pro-inflammatory cytokines expression and lead to brain ischemia/reperfusion injury during stroke." (PMID 32746852, 2020). "Increased immunoreactivity of SIRT1, Beclin 1, ATG7, LC3-I/II, and cleaved caspase-3 was also noted in stroke brains." (PMID 40724883, 2025). "An increased expression of SIRT1 and proteins essential for autophagy, including Beclin 1, autophagy-related proteins ATG3, ATG5, ATG7, ATG12-5, and LC3-II/I, was observed postmortem in the brains of stroke patients." (PMID 40724883, 2025).
Alzheimer disease (4 papers, 2022 to 2025). A progressive, neurodegenerative disease characterized by loss of function and death of nerve cells in several areas of the brain leading to loss of cognitive function such as memory and language. "At the same time, the survival of atg7 autophagy mutants as well as of Alzheimer’s disease model flies was not protected in both sexes." (PMID 36469518, 2022).
amyotrophic lateral sclerosis (4 papers, 2012 to 2024). Amyotrophic lateral sclerosis (ALS) is a neurodegenerative disease characterized by progressive muscular paralysis reflecting degeneration of motor neurons in the primary motor cortex, corticospinal tracts, brainstem and spinal cord. "Some studies have found that motor neuron-specific ATG7 knockout mice carrying the pathogenic mutation of SOD1 may induce Amyotrophic Lateral Sclerosis." (PMID 34661876, 2022). "On the other hand, upregulation of Atg7 attenuates degeneration of motor neurons in the context of amyotrophic lateral sclerosis and frontotemporal dementia." (PMID 32046105, 2020). "The expression of ATG7 was decreased in brain tissues from amyotrophic lateral sclerosis (ALS)-frontotemporal dementia (FTD) patients, and upregulation of ATG7 could alleviate motor neuron dysfunction associated with deficiency of TARDBP/TDP-43 (TAR DNA binding protein)." (PMID 38227600, 2024).
Ataxia (4 papers, 2015 to 2025). Ataxia refers to impaired coordination of voluntary muscle movement. "The neuronal Atg5 and Atg7 knockouts present with behavioral deficits and progressive motor dysfunction, such as ataxia." (PMID 25875846, 2015). "Along similar lines, recent findings in milder autophagy disorders with phenotypes limited to specific organ systems have stimulated the investigation of tissue‐specific pathomechanisms in autophagy disorders, for example, ATG7‐related NDDs or ATG5‐related ataxia." (PMID 39420677, 2025).
breast tumor (4 papers, 2021 to 2026). "The IRF1/autophagy-related gene−7 (ATG7) signaling pathway is also key to tamoxifen resistance in estrogen receptor-positive (ER+) breast tumors." (PMID 36226063, 2022). "We next explored whether ATG7 deletion stimulates fibroblast activation and thereby promotes breast tumor progression." (PMID 40707430, 2025). "The expression levels of ATG7 and LC3II were significantly higher in stage II and III breast tumor tissues compared to adjacent nontumor tissues." (PMID 33806593, 2021).
Cerebral ischemia (4 papers, 2018 to 2021). Restriction of arterial blood supply to the brain associated with insufficient oxygenation to support the metabolic requirements of the tissue. "Five key autophagy proteins, p62, LC3, ATG7, Beclin1, and pULK1, show differential expression in response to cerebral ischemia in males and females." (PMID 34359998, 2021). "Moreover, studies also proved that knocking out the ATG7 gene could effectively decrease the activation of caspase-3 and inhibit cell apoptosis in neonatal mice with cerebral ischemia injury." (PMID 34362425, 2021).
cholestasis (4 papers, 2022 to 2025). Impairment of the bile flow caused by obstruction within the liver, or outside the liver in the bile duct system. "Mice deficient in Atg5 or Atg7 exhibit increased accumulation of p62, which correlates with more severe intrahepatic cholestasis, suggesting that defective autophagy exacerbates cholestatic liver injury." (PMID 39061903, 2024). "In addition, hepatic deletion of autophagy-associated genes Atg5 or Atg7 lead to autophagy-deficient in mice, which promotes intracellular cholestasis with the increased level of bile acids." (PMID 35930537, 2022). "First, to verify and further define cholestasis-dependent changes in autophagy proteins in our PSC samples, expression of p62, Beclin1, LC3a/b, ATG5/12, ATG7, LAMP1 and LAMP2 was evaluated by Western blotting using lysates prepared from PSC liver tissue." (PMID 36378690, 2022).
esophageal cancer (4 papers, 2015 to 2021). A primary or metastatic malignant neoplasm involving the esophagus. "A large scale integrated genomic characterization of esophageal cancer revealed three subtypes, ESCC1-3, two of which displayed deep deletions in ATG7, the protein product of which mediates LC3 lipidation and AV formation." (PMID 31683722, 2019). "Furthermore, knockdown of Beclin 1 and autophagy-related protein 7 (ATG7) expression levels, in OE19 and KYSE450 esophageal cancer cells, enhanced the effects of 5-fluorouracil (5-FU), a chemotherapeutic agent used to treat esophageal cancer." (PMID 25322694, 2015). "Given the presence of deep deletions in the ATG7 gene and the presence of RPS6KB1-VMP1 gene fusions in subsets of esophageal cancer patients, it may be critical to take into account the impact of patient genetics upon the use of autophagy factors as biomarkers in esophageal cancer." (PMID 31683722, 2019).
Hypertension (4 papers, 2020 to 2025). The presence of chronic increased pressure in the systemic arterial system. "Specifically, placenta‐specific Atg7 knockout mice display hypertension and reduced placental growth factor levels, mirroring human PE characteristics (Trophoblast‐Specific Atg7 Knockout)." (PMID 40797362, 2025). "The levels of cleaved-caspase 3/caspase 3, cleaved-caspase 8/caspase 8, Bax/Bcl2, LC3 II/LC3 I, Beclin-1 and autophagy related 7 (ATG7) were increased in the heart of HSD rats with hypertension (HTN), and in hypertension-prone (HP) and hypertension-resistant (HR) rats." (PMID 33996809, 2021). "HSD increased the levels of LC3 II/LC3 I, Beclin-1, and ATG7 in the heart of rats with hypertension and non-hypertension." (PMID 33996809, 2021).
Hypoglycemia (4 papers, 2018 to 2025). A decreased concentration of glucose in the blood. "Previous studies have shown hypoglycemia in liver‐specific Atg7 knockout mice, and we now report the same in liver‐specific Atg3 knockout animals." (PMID 40420631, 2025). "Eighty percent of whole-body somatic atg7 KO mice die with lethal hypoglycemia during a 24-h fasting period." (PMID 29999454, 2018). "Previous reports describing Atg7Δ/Δ mice at this time point show they express little to no ATG7 protein in the liver and other tissues and are susceptible to fasting-induced hypoglycemia, but do not yet show signs of wasting or severe neurodegeneration." (PMID 39798881, 2025).